INS (insulin)
Diseases named in the same sentence as INS in open-access papers (continued):
Sharing a sentence is not in itself a finding about the gene and the disease.
diabetes (continued). "In vitro studies on breast cancer cell lines showed that the serum of patients with diabetes was a stronger mitogenic when using glargine as compared to other types of insulin." (PMID 24131755, 2013). "Perceiving insulin as beneficial is a crucial factor for diabetes patients commencing on insulin to accept insulin therapy." (PMID 24164794, 2013). "Peroxisome proliferator-activated receptor-γ (PPARγ) agonists such as rosiglitazone and pioglitazone are used to improve insulin sensitivity in patients with diabetes mellitus." (PMID 23577024, 2013). "In recent studies in humans, an inhaled dry powder formulation of recombinant regular human insulin has also shown favorable effects for diabetes." (PMID 23622115, 2013). "In this section the researchers introduce the demographic data, general knowledge about diabetes, general knowledge of insulin and glucagon use, general knowledge of complications, general knowledge of diabetic diet and general knowledge of physical exercise." (PMID 24171891, 2013). "The vast majority of patients reported being treated with anti-diabetic drugs and/or insulin, and at least one complication of diabetes was reported by nearly half of all patients." (PMID 23800376, 2013). "For example, leptin and insulin act on the hypothalamus to regulate energy balance and hepatic gluconeogenesis, and therefore, appear to control fasting hyperglycemia in diabetes." (PMID 23991090, 2013). "Therapy in use among those with diabetes was 58.8% dietary, 48.4% oral hypoglycaemic agents, 22.6% insulin and 12.9% herbal therapy." (PMID 23601475, 2013). "Diabetes mellitus is a metabolic disease due to disability in pancreas to either produce enough insulin or respond to insulin." (PMID 24551792, 2013). "Insulin treatment prevented the diabetes-induced body weight decrease and blocked the blood glucose increase." (PMID 23991188, 2013). "“I was actually scared of insulin because it requires injection” (2 years of insulin use/ 10 years of having diabetes)." (PMID 24164794, 2013). "Diabetes medicine such as metformin, sulfonyurea and insulin are available to all diabetes patients free of charge as part of the UC scheme." (PMID 23497447, 2013). "Among insulin-treated people with diabetes, mortality from neoplasms increased almost in all age groups between the study periods." (PMID 23837500, 2013). "Cumulative incidence and Cox Proportional Hazard Ratios (HRs) of diabetes-related complications in patients treated with human regular insulin or a rapid-acting insulin analogue." (PMID 24244557, 2013). "Experimental brain diabetes produced by intracerebral administration of streptozotocin (STZ) shares many features with AD and is treatable with insulin sensitizer agents, that is, drugs currently used to treat type 2 diabetes mellitus (T2DM)." (PMID 24228060, 2013). "Peripheral resistance to insulin can induce or precipitate type 2 diabetes mellitus (DM) and metabolic syndrome." (PMID 23577326, 2013). "More importantly, recently it was reported that the PPAR-α agonist fenofibrate prevents the development of diabetes in insulin-resistant obese OLETF rats." (PMID 23781121, 2013). "Many Type 2 Diabetes Mellitus (T2DM) patients refuse insulin therapy even when they require this modality of treatment." (PMID 24164794, 2013). "Attempts to cure diabetes mellitus using islet transplantation have been successful in providing a source for insulin secreting cells." (PMID 23762531, 2013). "The destruction or dysfunction of the insulin-producing beta cells of the pancreas contributes to a family of metabolic diseases known as diabetes mellitus." (PMID 23408910, 2013). "Insulin and oral agents for diabetes treatment were prescribed for 23.9% and 70.5% of the late elderly and non-elderly individuals, respectively." (PMID 23302697, 2013).
diabetes (continued). "After developing overt diabetes, half of the diabetic animals were implanted with insulin pellets to maintain their glucose levels in normal ranges (diabetic normoglycemic; DN group)." (PMID 23762878, 2013). "Animal models of diabetes have been used for the past 150 years and were instrumental in the discovery of insulin." (PMID 23762878, 2013). "Plasma insulin was increased in mice with streptozotocin-induced diabetes mellitus (DM) upon administration of the saponin fraction of the methanol extract of GS leaves or isolated triterpene glycosides." (PMID 24304585, 2013). "Diabetes mellitus (DM) is characterized by abnormal insulin secretion, derangements in carbohydrate-lipid metabolism, and chronic hyperglycemia." (PMID 23326534, 2013). "The patient was on insulin for diabetes (right-eye amaurosis due to diabetic retinopathy) and was being treated for hypothyroidism." (PMID 23670317, 2013). "Insulin resistance (IR), an impaired cellular, tissue and whole body response to insulin, is a major pathophysiological defect of type 2 diabetes mellitus." (PMID 23468892, 2013). "Type 1 diabetes mellitus is an autoimmune disease that results in permanent destruction of the insulin-producing cells in the pancreas and subsequent disturbance of glucose and lipid metabolism." (PMID 23573250, 2013). "Diabetes presented a quick and spontaneous remission observed by gradual increase of pancreatic insulin of these animals, however, during adult life, the animals showed a decrease of insulin secretion." (PMID 23878822, 2013). "Diabetes is a group of diseases marked by high levels of blood glucose resulting from defects in insulin production, insulin action, or both." (PMID 23839092, 2013). "Whatever he (doctor) says, I will follow because I trust him” (3 years of insulin use/ 6 years of having diabetes)." (PMID 24164794, 2013). "In the UK Prospective Diabetes Study (UKPDS), all therapies (insulin, metformin, SUs, lifestyle) were associated with an increasing HbA1c." (PMID 23841986, 2013). "Type 1 diabetes mellitus (T1DM) results from the autoimmune destruction of insulin-producing β cells of the pancreas." (PMID 23826312, 2013). "Human embryonic stem cells (hESCs) have the ability to form cells derived from all three germ layers, and as such have received significant attention as a possible source for insulin-secreting pancreatic beta-cells for diabetes treatment." (PMID 24324748, 2013). "At follow-up, women with type 2 diabetes had a diagnosis of diabetes for 18.8 (9.7) years, and the majority of participants (12/15 [80.0%]) were taking insulin or insulin in combination with another glucose-lowering intervention." (PMID 23530948, 2013). "A number of pathways are important for the development of obesity and/or diabetes, including but not limited to alterations in neurohumoral signaling, feeding behavior, energy balance, brain and peripheral inflammation, and insulin resistance." (PMID 23232494, 2013). "Basal levels of intraplatelet ROS were not different between healthy monkeys and monkeys receiving sufficient insulin to control their diabetes (well-controlled) or those receiving less insulin (poorly controlled)." (PMID 23841102, 2013). "It has been recently suggested that ER stress plays a central role in the development of insulin resistance and diabetes via the JNK-mediated inhibition of insulin activity." (PMID 24244369, 2013). "Compared with previous data at insulin initiation, our results show higher mean baseline HbA1c levels and longer mean diabetes duration." (PMID 24011395, 2013). "The results showed significant increase in glucose and decrease in insulin concentrations in diabetic group after administration of alloxan monohydrate and confirmed induction of diabetes (p < 0.05)." (PMID 25653789, 2013). "An interesting prospective cohort study performed in 9249 women aged ≥67 years analyzed the number of falls: a total of 629 (6.8%) women had diabetes, including 99 who used insulin." (PMID 23785355, 2013).
diabetes (continued). "Diabetes progression influenced important genes that were required for insulin expression in both OB- and HPC-derived cells." (PMID 23673084, 2013). "Mutations in the KATP channel genes and the proinsulin gene (INS) account for at least 50-75% of infancy-onset permanent monogenic diabetes in outbred populations." (PMID 24051999, 2013). "Treatment with insulin prolongs survival and improves glycemic control, and current standard diabetes treatment regimens with insulin replacement remain away from ideal." (PMID 23421382, 2013). "Patients with ketosis prone diabetes (KPD) are in the category of those who present with ketocidosis but after initial insulin therapy can stop insulin and revert to tablet treatment." (PMID 23841986, 2013). "At the end of the day, you just want to have a good life, right... not just physical, but your mental and soul as well” (2.5 years of insulin use/ 6 years of having diabetes)." (PMID 24164794, 2013). "The participants’ acceptance of insulin was influenced by their concerns and beliefs about diabetes and insulin." (PMID 24164794, 2013). "We also found insulin therapy to be among the main predictors of retinopathy in this type of diabetes." (PMID 24363502, 2013). "Although a diagnosis of diabetes before 6 months of life is highly suggestive of a genetic cause, in such cases other types of monogenic diabetes (due to mutations in KCNJ11, INS or ABCC8 genes) are more plausible and should be evaluated before MODY2." (PMID 24244580, 2013). "This novel TZD has low affinity for binding and activation of PPARγ and has insulin-sensitizing effects in mouse models of diabetes and ability to lower glucose in Phase 2 clinical trials." (PMID 23650507, 2013). "Other than effects of insulin on developing lungs, recent efforts towards developing inhaled insulin formulations for diabetes management have provided interesting insights into direct effects of insulin on the mature lung." (PMID 24204385, 2013). "Control or Ab/IL-2 treated pancreata were processed for immunofluorescence staining with insulin and Ki67, within the first or second week after diabetes onset." (PMID 24205242, 2013). "In conclusion, this study showed that 30 units of insulin were necessary when performing AGT in pregnant women with diabetes mellitus." (PMID 23533796, 2013). "Age and use of oral medication and insulin were the strongest predictors for membership in a diabetes-related primary healthcare profile with high utilisation." (PMID 23289605, 2013). "-It would be fun to know just, yes, that there will be the remedy for diabetes within 15 years and...it is... they have been talking a lot about finding a certain remedy to regain your insulin production." (PMID 23805322, 2013). "Earlier investigators used STZ models of diabetes and identified that the prolongation of action potential is reversed by additional supplementation of insulin in the perfusion medium during action potential recording." (PMID 23573265, 2013). "Automated closed-loop control of blood glucose concentration is a daily challenge for type 1 diabetes mellitus, where insulin and glucagon are two critical hormones for glucose regulation." (PMID 24260042, 2013). "While professionals are primarily preoccupied with values of HbA1c, glucose and insulin doses, patients deal with blood glucose self-monitoring, insulin applications and their diabetes diet regimen and know about their personal compliance." (PMID 24344648, 2013). "Quantitation of β-cell function is critical in better understanding of the dynamic interactions of insulin secretion, clearance and action at different phases in the progression of diabetes." (PMID 23886319, 2013). "NOD mice with severe diabetes at onset (blood glucose >400mg/dl), were treated with insulin for 4 weeks after the initial onset of disease." (PMID 24205242, 2013).
diabetes (continued). "This was followed by a more significant decrease in plasma glucose and a more significant increase in plasma insulin and C-peptide levels which continued for 10 months after induction of diabetes reaching almost normal basal levels." (PMID 24279645, 2013). "For example, insulin, a drug commonly used to treat diabetes, in the Western world requires refrigeration." (PMID 23561029, 2013). "There are five major classes of oral antihyperglycemic drugs and a wide variety of insulin (short acting / long acting) available for comprehensive management of Diabetes." (PMID 23822656, 2013). "Among people with insulin-treated diabetes, significant increase was observed in excess mortality from cancer among women." (PMID 23837500, 2013). "It found that there were some excellent individual health services and diabetes-related policies in Ireland, such as the provision of free insulin and free diabetes medicine to young adult patients." (PMID 24168159, 2013). "The cross-talk between insulin and angiotensin II signalling pathways plays a significant role in the co-occurrence of diabetes and hypertension." (PMID 24400038, 2013). "The blood glucose level of diabetes patients often needs to be closely monitored, and it remains as an open question on how much the right dosage of insulin and the frequency of the doses should be given to maintain an appropriate level of blood glucose." (PMID 24163813, 2013). "Unfortunately, in most patients with diabetes treated with intensive insulin therapy, the CRR is impaired as a consequence of recurrent episodes of hypoglycemia (RH)." (PMID 23894333, 2013). "Further large-scale prospective studies, where body fat is adequately accounted for and which enroll various ethnic groups, are needed to further elucidate the role of dietary magnesium in improving insulin function and preventing diabetes." (PMID 23472169, 2013). "The liver is an insulin-dependent tissue that plays a vital role in glucose and lipid homeostasis and is severely affected in diabetes." (PMID 24204387, 2013). "For people with non-insulin-treated diabetes, the excess overall mortality in 2003–2007 was nearly twofold both among men and women compared to the people without diabetes." (PMID 23837500, 2013). "In one study, more than 50% of patients with insulin dependent diabetes mellitus missed their insulin dose." (PMID 24070224, 2013). "E4orf1 inducible cell line described here provides an opportunity to test an important template for proximal insulin signaling-independent glucose uptake, and should help in carefully elucidating signaling important in diabetes, and obesity." (PMID 23544159, 2013). "Functional insulin producing cells were responsive to normal glucose challenge and were deemed useful for potential diabetes therapy." (PMID 23762531, 2013). "Maximum insulin dose was associated with HOMA-IR, OR: 2.00, after adjustment for family history of diabetes, and 2-h OGTT glucose." (PMID 23819910, 2013). "Diabetes mellitus is a family of metabolic diseases that can result from either destruction or dysfunction of the insulin-producing beta cells of the pancreas." (PMID 23408910, 2013). "Diabetes mellitus is a chronic disease of uncontrolled hyperglycaemia, which is secondary to defects in insulin secretion, the action of insulin, or both." (PMID 23983688, 2013). "In particular, few data are available regarding the roles of baseline HbA1c levels and the duration of diabetes for predicting future need for insulin therapy." (PMID 24011395, 2013). "Protein tyrosine phosphatase 1B (PTP1B) plays a major role in the negative regulation of insulin signaling, and is thus considered as an attractive therapeutic target for the treatment of diabetes." (PMID 23612372, 2013).
diabetes (continued). "Such activities included wearing CSII devices (Continuous Subcutaneous Insulin Infusion), or, in the case of two young adults recruited from the clinical setting, joining diabetes-related support groups on social media sites such as Facebook." (PMID 23885644, 2013). "In conclusion, oxytocin and its analogs have multi-level effects in improving weight control, insulin sensitivity and insulin secretion, and bear potentials for being developed as therapeutic peptides for obesity and diabetes." (PMID 23700406, 2013). "Exploring patients’ concerns and beliefs about diabetes and insulin is crucial to assist physicians in delivering patient-centered care." (PMID 24164794, 2013). "Insulin regulation of sugar homeostasis has been extensively investigated because of its importance in diabetes and related syndromes." (PMID 24223128, 2013). "The glucose lowering treatment for the patients with diabetes, prior to their hospitalization, was diet alone in 13.1%, oral therapy in 60%, insulin in 19%, and combination therapy in 7% of the patients." (PMID 23861680, 2013). "In fact, the onset of diabetes depends on the ability of β-cells to respond to the increased demand for insulin that results from insulin resistance, with β-cells failure causing type-2 diabetes." (PMID 24205230, 2013). "During diabetes there will be high secretory demand for insulin placed on the pancreatic β-cells to counteract hyperglycemia." (PMID 23835113, 2013). "Type 2 diabetes mellitus (T2DM) is characterised by defects in both end-organ responsiveness to insulin (insulin resistance) and the regulation of insulin release by pancreatic β cells." (PMID 23717413, 2013). "Beta-cell impairment exists in insulin-sensitive offspring of patients with type 2 diabetes, suggesting beta-cell dysfunction to be a major defect determining diabetes development in offspring of diabetic mothers." (PMID 23998129, 2013). "Following a period of uncontrolled diabetes mellitus in humans (i.e., pre-diagnosis), insulin administration is the therapeutic standard, and is well studied in terms of regulating muscle protein turnover." (PMID 24391596, 2013). "Diabetes effect on tissue function is due to inadequate insulin production and subsequent reduction of effect of that hormone deteriorates Sertoli and Leydig cells function." (PMID 25050292, 2013). "Formulations of exogenous insulin used to manage diabetes vary in their affinity for the insulin receptor, IGF-1." (PMID 24282613, 2013). "We review the molecular basis of the involvement of morbidly high concentrations of endogenous or therapeutic insulin and of insulin-like growth factors in the progression from obesity to diabetes and finally to cancer." (PMID 23983688, 2013). "Certain monogenic subtypes of diabetes have resulted in dramatic success of transferring from insulin therapy to oral sulfonylurea therapy, based on the location of the genetic defect upstream from the target of the sulfonylurea drug." (PMID 23766565, 2013). "Further, in the present study those with known diabetes (those taking oral agents or insulin) were excluded." (PMID 23379469, 2013). "Both detecting pre-diabetes by medical examination and finding insulin abnormalities are important for early diagnosis of diabetes." (PMID 23691063, 2013). "Both groups were similar for ethnicity, BMI, cardiovascular co-morbidities, diabetes duration, HbA1c, and insulin treatment (p>0.05)." (PMID 24260240, 2013). "Limited evidence exists on the effectiveness of external diabetes support provided by diabetes specialists and community retail pharmacists to facilitate insulin-prescribing in family practice." (PMID 23433347, 2013). "Few studies are available evaluating the impact of rapid-acting insulin analogues on long-term diabetes outcomes." (PMID 24244557, 2013). "We found that excess CHD mortality was particularly high among insulin-treated people with diabetes." (PMID 23837500, 2013).